HEPH (hephaestin)
Description:
Plasma membrane ferroxidase that mediates the extracellular conversion of ferrous/Fe(2+) iron into its ferric/Fe(3+) form. Couples ferroportin which specifically exports ferrous/Fe(2+) iron from cells to transferrin that only binds and shuttles extracellular ferric/Fe(3+) iron throughout the body. By helping iron transfer from cells to blood mainly contributes to dietary iron absorption by the intestinal epithelium and more generally regulates iron levels in the body (By similarity).
Synonyms: KIAA0698; CPL
Tractability: Antibody: UniProt places it where antibodies can reach, with high confidence; its Gene Ontology location is reachable by antibodies, with high confidence; UniProt predicts a signal peptide or a membrane-spanning region. PROTAC: ubiquitination databases record sites on it.
Gene: Protein-coding gene on chromosome X (66,162,483 to 66,268,910, forward strand). Ensembl gene ENSG00000089472.
Subcellular location: Basolateral cell membrane
Pathways (Reactome):
Transport of small molecules: Iron uptake and transport; Metal ion SLC transporters
Disease: Defective SLC40A1 causes hemochromatosis 4 (HFE4) (duodenum)
Gene Ontology:
Molecular function: ferroxidase activity; protein binding; copper ion binding; oxidoreductase activity
Biological process: intestinal iron absorption; multicellular organismal-level iron ion homeostasis; positive regulation of iron export across plasma membrane
Cellular component: basolateral plasma membrane; plasma membrane; perinuclear region of cytoplasm
Homologues: Orthologues: chimpanzee HEPH (99% identical), macaque HEPH (97% identical), pig HEPH (89% identical), rabbit HEPH (89% identical), guinea pig HEPH (86% identical), mouse Heph (86% identical), rat Heph (85% identical), tropical clawed frog hephl1 (52% identical), zebrafish hephl1b (48% identical). Paralogues in human: HEPHL1 (49% identical), CP (43% identical), F8 (34% identical), F5 (33% identical), CNTNAP5 (16% identical), CNTNAP3 (16% identical), CNTNAP4 (15% identical), CNTNAP3B (15% identical), CNTNAP2 (14% identical), NRXN3 (13% identical), NRXN2 (13% identical), NRXN1 (13% identical), and 23 more.
Diseases named in the same sentence as HEPH in open-access papers:
HEPH is named in the same sentence as 55 diseases in open-access papers, as found by Europe PMC text mining. Sharing a sentence is not in itself a finding about the gene and the disease. The quoted sentences say what the papers report.
breast carcinoma (10 papers, 2017 to 2023). "The most important observation is that decreased HEPH expression is significantly associated with a poor prognosis in breast cancer, and the combination of high G9a and low HEPH is associated with shorter survival times." (PMID 28819251, 2017). "If the repressive effect of G9a on HEPH expression is important for the growth-promoting functions of G9a, we would expect loss of HEPH to facilitate breast cancer cell survival." (PMID 28819251, 2017). "Furthermore, a tissue microarray analysis from 75 breast cancer patients revelated that high G9a expression and low hephaestin expression are associated with poor prognosis." (PMID 34831207, 2021). "In addition, another important finding is that high G9a and low HEPH are associated with poor prognosis in breast cancer patients." (PMID 28819251, 2017). "In this study, we indicated that HEPH, another important iron-associated protein that makes a substantial contribution to the regulation of cellular iron levels, has a key role in the clinical behavior of breast cancer." (PMID 28819251, 2017). "G9a exerts its oncogenic function in breast cancer by repressing hephaestin and destruction cellular iron homeostasis." (PMID 37143582, 2023). "Overexpression of G9a results in suppression of hephaestin and leads to iron accumulation in breast cancer cells, which stimulates cell growth." (PMID 30250199, 2018). "A recent study showed that G9a regulated breast cancer growth by repressing ferroxidase hephaestin, while G9a inhibition led to a marked down-regulation of c-Myc." (PMID 30348169, 2018). "In the present study, we discover that G9a represses HEPH expression, changes cellular iron homeostasis, and stimulates breast cancer growth." (PMID 28819251, 2017). "As with the microarray profiling data, HEPH was noticeably up-regulated in G9a-knockdown breast cancer cells (MCF-7, MDA-MB-231, ZR-75-30, S1, SK-BR-3 and MDA-MB-435) compared with the control." (PMID 28819251, 2017). "To further confirm the importance of HEPH regulation by G9a in tumorigenesis, we suppressed HEPH expression in G9a-silenced breast cancer cells." (PMID 28819251, 2017). "Taken together, our findings were consistent with the model whereby elevated G9a in breast cancer allows aberrant hypermethylation of the HEPH promoter, suppressing HEPH transcription, which then increases intracellular LIP and drives breast tumor progression." (PMID 28819251, 2017). "We proved that HEPH is downregulated by G9a in breast cancer cell lines and in human breast cancer samples." (PMID 28819251, 2017). "Here the authors propose a mechanism through which G9a promotes breast cancer by regulating iron metabolism through the repression of ferroxidase hephaestin." (PMID 28819251, 2017). "Identifying these key repressive molecules that are responsible for G9a-mediated transcriptional repression of HEPH is important for a better understanding of complicated epigenetic regulation during breast cancer progression." (PMID 28819251, 2017). "Here we report that G9a exerts its oncogenic function in breast cancer by repressing hephaestin and destruction cellular iron homeostasis." (PMID 28819251, 2017). "Meanwhile, overexpression of HEPH in breast cancer cells led to a decrease in cellular iron content, which confirmed the role of HEPH in exporting iron out of cancer cells." (PMID 28819251, 2017). "In contrast, overexpression of G9a reduced the mRNA and protein levels of HEPH in breast cancer cells." (PMID 28819251, 2017). "Additionally, aberrant expression of HEPH has been observed in BT-474 and T-47D breast cancer cells." (PMID 36620542, 2022). "All these data strongly suggest that G9a inhibits HEPH expression in breast cancer." (PMID 28819251, 2017). "In the present study, we investigated the novel G9a target gene HEPH in breast cancer." (PMID 28819251, 2017). "Furthermore, high G9a expression and low hephaestin expression correlate with poor survival of breast cancer are investigated." (PMID 28819251, 2017).
breast carcinoma (continued). "Thus, our observations raise the exciting possibility that G9a and HEPH are potential prognostic markers of breast cancer progression and targets for therapeutic intervention." (PMID 28819251, 2017). "Specifically, in breast cancer, the expression of iron-related genes, including TFR1, HEPH, and FPN, is altered, and this aberrant expression is associated with patient clinical outcomes." (PMID 37080959, 2023). "G9a, an H3K9 methyltransferase associated with HDAC1 and YY1, a member of the Krüppel family of transcription factors, forms a silencing multi-molecular complex targeting the repression of the ferroxidase Hephaestin gene, which codes a co-factor of FPN involved in ferric export in breast cancer." (PMID 34831207, 2021). "Our previous study shows that ferroxidase hephaestin (HEPH) is repressed by G9a, a H3K9 methyltransferase, which forms complex with transcription factor YY1 and HDAC1, leading to cellular LIP increase and promoting breast cancer proliferation." (PMID 30591630, 2018). "The data revealed that ferroxidase HEPH is among the most significantly upregulated transcripts by G9a inhibition, for which no function in breast cancer has been ascribed so far." (PMID 28819251, 2017). "The representative immunohistochemistry analysis of 75 breast cancer specimens revealed inverse staining patterns between G9a and HEPH expression in breast cancer tissues, independent of tumor type (tested by Pearson’s nonparametric correlation test, correlation coefficient: −0.678, P < 0.05)." (PMID 28819251, 2017).
anemia (6 papers, 2013 to 2021). A reduction in the number of red blood cells, the amount of hemoglobin, and/or the volume of packed red blood cells. "Deletion or mutation of the hephaestin gene leads to systemic anemia with iron accumulation in the intestinal epithelium." (PMID 28880952, 2017). "The knockout strains, however, both developed a microcytic, hypochromic anemia, suggesting severe iron deficiency and confirming that hephaestin plays an important role in body iron acquisition." (PMID 24896847, 2014). "The mechanism of anemia in copper deficiency is possibly related to the role of copper-dependent enzymes, such as ceruloplasmin, hephaestin, and cytochrome-c oxidase in iron metabolism and transportation." (PMID 23984326, 2013). "Deficiencies in hephaestin can lead to anemia due to hephaestin's role in iron egress from intestinal enterocytes." (PMID 23984326, 2013). "Furthermore, a decreased activity of hephaestin, a multicopper ferroxidase, causes anemia and impaired dietary iron absorption." (PMID 34946818, 2021). "Hephaestin is mutated in the sex-linked anemia mouse, resulting in iron deficiency." (PMID 24896847, 2014). "Mice with intestinal knockout of HEPH had a microcytic anemia at 6–7 weeks of age, and improvement in most hematological parameters was seen by 10–12 weeks of age." (PMID 24896847, 2014). "Anemia of newborn mice may be explained by insufficient iron feeding of the fetus due to decreased ferroxidase activity of hephaestin in the placenta." (PMID 23807651, 2013). "Our findings would suggest that changes in ferroportin and hephaestin expression do not explain the intestinal pathophysiology of anemia in celiac disease but may rather reflect the immaturity of the epithelium of the atrophic duodenal mucosa." (PMID 33673530, 2021).
colon cancer (4 papers, 2014 to 2023). "Exosomal miR-24-3p from cancer-associated fibroblasts enhances methotrexate resistance and inhibits the apoptosis of colon cancer cells by suppressing caudal type homeobox 2 (CDX2) or hephaestin (HEPH) expression." (PMID 36612314, 2023).
retinal degeneration (4 papers, 2012 to 2022). Degeneration of the retina. "Similarly, mice with targeted mutation of the iron exporter ceruloplasmin and its homolog hephaestin showed age-related retinal iron accumulation and retinal degeneration with features resembling human age-related macular degeneration (AMD)." (PMID 23825457, 2013). "Mice that model human aceruloplasminemia through knockout of ceruloplasmin (Cp) and hephaestin (Hp), its homolog, have been studied, showing progressive retinal degeneration." (PMID 30360383, 2018). "Several studies have shown the neuroprotective effects of DFP on different retinal degeneration models induced by sodium iodate, tunicamycin and light as well as Ceruloplasmin/Hephaestin double-knockout mice and hereditary retinal degeneration caused by the rd6 mutation." (PMID 36385152, 2022). "Mice lacking key genes of iron homeostasis – ceruloplasmin, hephaestin and hepcidin — developed retinal degeneration with features of AMD." (PMID 22371024, 2012).
lung adenocarcinoma (3 papers, 2021 to 2025). A carcinoma that arises from the lung and is characterized by the presence of malignant glandular epithelial cells. "The importance of hephaestin in lung cancer iron homeostasis was the subject of a recent report, and reduced expression of hephaestin is associated with poor prognosis for lung adenocarcinoma and squamous cell carcinoma." (PMID 37932771, 2023). "In this study we explored the prognostic value of HEPH and its expression pattern in the most prevalent histotypes of lung cancers, namely lung adenocarcinoma and lung squamous cell carcinoma." (PMID 34094919, 2021).
lung carcinoma (3 papers, 2021 to 2025). "We recently identified a single-nucleotide polymorphism within HEPH gene, leading to a missense variation of this multicopper ferroxidase, which confers protection against asbestos-dependent malignant pleural mesothelioma and lung carcinoma in exposed subjects." (PMID 34094919, 2021). "Based on bioinformatic evidence, also HEPH mRNA expression levels are downregulated in several malignancies, including lung cancer and, similarly to FPN1, such down-regulation correlates with poor prognosis." (PMID 34094919, 2021). "In the present study, supported by bioinformatic evidence, we identified HEPH, a protein involved in exporting iron out of the cell, as a promising predictor of clinical prognosis in lung cancer." (PMID 34094919, 2021). "Bioinformatic analysis based on mRNA expression dataset, indicates HEPH as a potential novel prognostic biomarker for lung cancer pathologies." (PMID 34094919, 2021). "In this context HEPH expression, if further confirmed by retrospective studies on a broader cohort of patients, could serve as a potential prognostic marker in lung cancer pathogenesis." (PMID 34094919, 2021). "Given our interest in better understanding the role iron dysregulation may exert in lung cancer development and prognosis, we evaluated HEPH mRNA expression levels in the most prevalent histological types, LUAD and LUSC, as compared to normal tissue, utilizing the GEPIA database." (PMID 34094919, 2021). "The results showed that, in both types of lung cancer, HEPH expression had a significant negative correlation with tumor purity, the parameter that identifies the proportion of cancer cells present in the tumor tissue." (PMID 34094919, 2021).
aceruloplasminemia (2 papers, 2018 to 2019). An adult-onset disorder of neurodegeneration with brain iron accumulation (NBIA) characterized by anemia, retinal degeneration, diabetes and various neurological symptoms. "In fact, only the simultaneous ablation of CP and hephaestin (HEPH) genes in mice is able to recapitulate symptoms consistent with those shown by aceruloplasminemia patients, suggesting that hephaestin can compensate the lack of CP in mice, but not in humans." (PMID 30744104, 2019).
age-related macular degeneration (2 papers, 2013 to 2021). Age-related loss of vision in the central portion of the retina (macula), secondary to retinal degeneration. "CP and HEPH are co-expressed in retina and combined loss lead to age-related macular degeneration (AMD)." (PMID 33917579, 2021).
breast tumor (2 papers, 2017 to 2021). "Ferroxidase HEPH has recently been shown to play a role in breast tumor cell growth; in particular its decreased expression has been significantly correlated with poor survival in affected patients." (PMID 34094919, 2021). "The results showed a noteworthy inverse correlation between G9a and HEPH expression, independent of breast tumor type." (PMID 28819251, 2017).
iron deficiency (2 papers, 2009 to 2014). "A similar phenotype of systemic iron deficiency resulting from accumulation of absorbed iron in the duodenal epithelium has been reported in sex-linked anemia (Sla) mice due to a mutation in the intestinal ferroxidase Hephaestin." (PMID 19568430, 2009).
lung squamous cell carcinoma (2 papers, 2021 to 2025). "DMP1, GP1BA and HEPH remained associated with lung squamous cell carcinoma." (PMID 41340014, 2025).
celiac disease (1 paper, 2021). An autoimmune genetic disorder with an unknown pattern of inheritance that primarily affects the digestive tract. "The present results suggest an iron status-independent alteration of ferroportin and hephaestin proteins in children with histologically confirmed celiac disease." (PMID 33673530, 2021). "The results showed the stained area of ferroportin to be increased and the saturation of hephaestin to be decreased in celiac disease patients compared with controls." (PMID 33673530, 2021). "The main finding of the present study was an increased expression of ferroportin and a decreased expression of hephaestin in children with histologically confirmed celiac disease compared with the non-celiac controls." (PMID 33673530, 2021). "Additionally, a negative correlation between the saturation of hephaestin and sTfR levels was shown among all of the children although this was not seen in celiac disease patients when evaluated separately." (PMID 33673530, 2021). "We therefore aimed to investigate possible altered transporter protein expression by staining the DMT, DCYTB, ferroportin, hephaestin and TfR1 in duodenal biopsies of children with histologically confirmed or potential celiac disease and autoantibody-negative controls." (PMID 33673530, 2021).
colorectal carcinoma (1 paper, 2022). A malignant epithelial neoplasm that arises from the colon or rectum and invades through the muscularis mucosa into the submucosa. "Low expression of HEPH results in dysregulation of iron homeostasis and is associated with the occurrence of colorectal carcinoma." (PMID 36620542, 2022).
metastatic tumors (1 paper, 2021). "In order to expand the analysis to other cancer types, we examined HEPH expression using UALCAN to analyse TCGA RNA-sequencing and patients’ clinical data from 33 different cancer types, including several metastatic tumors." (PMID 34094919, 2021).
microcytic anemia (1 paper, 2024). Anemia in which the red blood cell volume is decreased. "Mutations in HEPH can cause severe microcytic anemia in mice." (PMID 39682483, 2024).
migraine (1 paper, 2012). "The strongest effect SNP (rs102834, joint P = 1.63×10−5) is located within the 5′UTR of the HEPH gene, which is involved in iron homeostasis in the brain and may represent a novel pathway for involvement in migraine pathogenesis." (PMID 22666411, 2012).
Obesity (1 paper, 2017). Accumulation of substantial excess body fat. "Rather, it was suggested that decreased expression of iron absorption related duodenal enzymes, such as duodenal cytochrome B (Dcyt1b) and hephaestin, could affect iron deficiency in obesity." (PMID 28228829, 2017).
ovarian carcinoma (1 paper, 2023). A malignant neoplasm originating from the surface ovarian epithelium. "The expression of CYBRD1, LRP2, TFRC, SLC22A17, HEPH, SLC39A14, and PCBP2 involved in iron import was associated with poor OS of ovarian cancer, whereas the expression of LCN2, CP, SLC46A1, STEAP3, and LTF in this process was associated with improved OS in ovarian cancer." (PMID 38186569, 2023).
schizophrenia (1 paper, 2016). A major psychotic disorder characterized by abnormalities in the perception or expression of reality. "There are 4 genes, SOX9, HEPH, AQP1, and SDC3 as susceptible genes, and it was already reported that SDC3 has a weak association with schizophrenia in related GWAS." (PMID 27510319, 2016).
thoracic cancer (1 paper, 2025). A primary or metastatic malignant neoplasm affecting the tissues of the thorax. "In a previous study, we identified a coding SNP in the hephaestin gene (HEPH) that protects against developing asbestos-related thoracic cancer." (PMID 40141249, 2025).